ASS1 (argininosuccinate synthase 1)
Diseases named in the same sentence as ASS1 in open-access papers (continued):
Sharing a sentence is not in itself a finding about the gene and the disease.
cancer (continued). "Treatment with SPA and LM-2I results in significant enhancement of ASS1 enzymatic activity in cancer cells, particularly in those cancer cells with low ASS1 expression, leading to the inhibition of cancer cell proliferation." (PMID 33859183, 2021). "ASS1 expression in cancer cells would allow Arg fueling of iNOS+TILs and enhance anti-tumor immunity." (PMID 34344457, 2021). "ASS1 expression was higher in HCC cells in the 3D culture system than in the 2D system, which illustrates the importance of 3D culture in cancer biologic studies and implicates ASS1 as a new target for anti-HCC therapeutics." (PMID 33838671, 2021). "This was further supported by demonstration of increased CAD (carbamoyl-phosphate synthetase 2, aspartate transcarbamylase, and dihydroorotase) activity in ASS1 silencing cancer cells." (PMID 33500708, 2021). "Cancer is thought to silence ASS1 to free aspartate pools for the biosynthesis that is associated with rapid cell division." (PMID 33478587, 2021). "Many cancers silence the metabolic enzyme argininosuccinate synthetase 1 (ASS1), the rate-limiting enzyme for arginine biosynthesis within the urea cycle." (PMID 33478587, 2021). "Cancer cells often downregulate the aspartate-consuming enzyme argininosuccinate synthase (ASS1) in the urea cycle to increase the aspartate availability for nucleotide biosynthesis." (PMID 34829708, 2021). "It is estimated that more than 70% of cancers are arginine-auxotrophs due to the low expression of ASS1 24, and because treatment can be guided by the level of ASS1 expression, making it an attractive option for cancer therapy." (PMID 33664852, 2021). "Through arginine synthesis, ASS1 plays critical key roles in the production of nitric oxide (NO), which paradoxically exhibits both cancer-promoting and -restricting effects depending on the cellular environment." (PMID 33838671, 2021). "Given the importance of arginine in cellular processes and being the most consumed amino acids in the inner mass of tumors, it is counter-intuitive that ASS1 is epigenetically suppressed in cancer cells." (PMID 34298755, 2021). "The somatic silence of ASS1 is very common in various types of cancers, however, the role of ASS1 in cancer is unclear." (PMID 33859183, 2021). "ASS1, which indirectly produces arginine in the urea cycle, is often decreased or even abolished through epigenetic silencing in many cancers, including SCLC." (PMID 34072010, 2021). "In our study, overexpression of ASS1 in different types of arginine-auxotrophic cancer cells gave variable degrees of ADI resistance." (PMID 33664852, 2021). "Arginino succinate synthetase (ASS1) produces endogenous arginine from citrulline, however, many cancer cells exhibit arginine auxotrophy e.g., due to ASS1 deficiency." (PMID 34041023, 2021). "It has been recently reported that decreased activity of ASS1 in cancers supports proliferation of cancer cells by facilitating pyrimidine synthesis." (PMID 33859183, 2021). "In the present study, we have demonstrated that SPA and its derivatives significantly inhibit cancer cell proliferation and tumor growth by activation of ASS1 in tumors." (PMID 33859183, 2021). "The absence or presence of ASS1 differentiate the cancer cell lines into arginine complete auxotrophic or partial auxotrophic, respectively." (PMID 32390765, 2020). "Cancers that silence ASS1 have been shown to have a more aggressive clinical course, as silencing is associated with poorer overall survival and metastasis-free survival in numerous subtypes of cancer." (PMID 32814773, 2020). "Still, ASS1 is reported to be epigenetically silenced in some cancer types, making them sensitive to antineoplastic therapy based on arginine-deprivation." (PMID 32872669, 2020). "It has been previously reported that about 50% of cancer cells from patients lack ASS1, which are auxotrophic for arginine." (PMID 32353864, 2020).
cancer (continued). "This indicates that ASS1 expression and arginine concentration play a crucial role in cancer metastasis." (PMID 32390765, 2020). "As an enzyme responsible for the biosynthesis of arginine in most body tissues, ASS1 was downregulated in multiple diverse cancers to reprogram arginine metabolism to make tumor cells more aggressive." (PMID 33200655, 2020). "Of the 10 proteins, the preceding text showed that some studies identified RRM2, PLOD2, MKI67, MCM5, and CKD1 promoted cancer progression and FBP1, FBP2, ENO3, GPD1, and ASS1 inhibited cancer progression, which was consistent with our results." (PMID 33200655, 2020). "Cancer cell lines with low expression levels of ASS1 were found to be sensitive to NEI-01 treatment." (PMID 32353864, 2020). "Mechanistically, reduction of ASS1 expression promotes cancer cell proliferation by shunting Asp towards pyrimidine biosynthesis." (PMID 31903153, 2020). "Thereby, ASS1 gene is critical for the growth of human cancers, due to the role of L-arginine in different aspects of tumour metabolism and the immune system." (PMID 31748515, 2019). "Recent studies demonstrate a correlation between urea cycle alteration and cancer cell proliferation, where expression of argininosuccinate synthase (ASS1) correlates with the amount of aspartate channeled into pyrimidine pathway to fuel cancer growth." (PMID 31861288, 2019). "Depletion of arginine induced by PEGylated arginase 1 (ARG1) (BCT-100) has shown anticancer effects in arginine auxotrophic cancers that lack argininosuccinate synthetase (ASS1) and ornithine transcarbamylase (OTC)." (PMID 30808864, 2019). "The downregulated ASS1 expression in these cancer cells increases the aspartate pool, which can be channeled to CAD for the synthesis of pyrimidines." (PMID 31108873, 2019). "Whatever the benefit, OTC downregulation renders cancer cells sensitive to treatment with human arginase, independently of ASS1 expression." (PMID 30108309, 2018). "Another urea cycle enzyme that functions in the arginine-citrulline cycle, ASS1, is also overexpressed in various human cancers, including in lung, colon, gastric and ovarian cancer." (PMID 30082427, 2018). "Nevertheless, it is also possible that ASS1 downregulation promotes cancer by decreasing the availability of arginine for NO synthesis." (PMID 30082427, 2018). "Pegylated arginine deiminase targets cancer cells defective in ASS1 expression, while pegylated arginase I targets a broader spectrum of cancer cells, which are defective in OTC and/or ASS1 expression." (PMID 28750681, 2017). "ADI-cell-penetrating fusion protein complex is designed to overcome ADI-resistance in ASS1-expressing cancer cells." (PMID 28750681, 2017). "This is also arginine auxotrophic cancer whose growth is inhibited by ADI-PEG 20 in vitro due to very low ASS1 levels." (PMID 28938609, 2017). "We have selected 16 ASS1-low cancer cell lines as well as a control ASS1-high cell line (N87) to investigate the effect of ADI-PEG 20 treatment on the expression of the well-characterized immune checkpoint inhibitor PD-L1." (PMID 28938609, 2017). "In many types of cancers, the expression of argininosuccinate synthase (ASS1) is silenced epigenetically, rendering the cells dependent on an exogenous supply of arginine." (PMID 27635066, 2016). "ASS1 knockdownsignificantly reduced liver metastasis in mice after the intrasplenic implantationof 3IB2 cancer cell clones." (PMID 25928182, 2015). "ASS1 silencing led to a decrease inthe expression of the ASS1 protein in MKN45 cancer cells compared with parentaland vector control (VC) cells." (PMID 25928182, 2015). "In this report, we have found that decreased ASS1 protein expression or argininedepletion inhibits cancer cell migration." (PMID 25928182, 2015). "Studies have shown that, in order to achieve long-term resistance to L-arg deprivation therapy, cancer cells may upregulate ASS1 expression in a MYC-dependent manner." (PMID 41295280, 2025).
cancer (continued). "Indeed, silencing ASS1 in cancer cells has been shown to suppress the urea cycle and redirect available aspartate into pyrimidine biosynthesis." (PMID 39920310, 2025). "However, due to the silencing of argininosuccinate synthase 1 (ASS1), certain tumors lose the ability to synthesize Arg, presenting a promising opportunity to combat cancer." (PMID 40723225, 2025). "Research indicates that the majority of cancer types, such as melanoma, bladder cancer, myxofibrosarcoma, lymphoma, and others, demonstrate arginine auxotrophy attributed to the decreased expression of ASS1." (PMID 41304979, 2025). "Indeed, the silencing of ASS1 in NMFs abolished the rescue of the cancer cells’ survival by fibroblasts." (PMID 41511309, 2025). "In our study, we defined low ASS1 expression as less than 10% positive cancer cells and ASS1 loss as the complete absence of ASS1 expression in the tumor cells." (PMID 41300990, 2025). "Other types of cancer cells that experience arginine starvation adapt by re-expressing ASS1." (PMID 39920310, 2025). "For example, in both ccRCC and HCC that express low levels of ASS1, the cancer cells concomitantly repress arginases (ARG1/2) and polyamine synthesis enzyme agmatinase (AGMAT) to maintain a high intracellular arginine concentration after assimilating arginine from the extracellular environment." (PMID 39920310, 2025). "Alterations of the urea cycle toward maximizing the use of nitrogen for macromolecules rather than disposal lead to impairment of the arginine synthesis machinery in cancer, as illustrated by the downregulation of the rate-limiting enzyme ASS1 across multiple cancers." (PMID 40253325, 2025). "Cancer cells become reliant on arginine when their excessive demand coincides with the impairment of intrinsic arginine production controlled by the rate-limiting enzyme argininosuccinate synthase 1 (ASS1)." (PMID 40253325, 2025). "In addition, similar pathway alterations were observed in cancer cells following either ASS1 knockdown or an AFD, underscoring the need for coordinated metabolic adaptation to both cell-intrinsic and systemic arginine deficiency." (PMID 41511309, 2025). "Additionally, previous study has proved that ASS1 is a new tumor repressor via epigenetic mechanism and downregulated in cancers such as ovarian cancer." (PMID 38218942, 2024). "Cancer cells may exhibit increased expression of argininosuccinate synthase (ASS1), a key enzyme in the Arginine biosynthesis pathway, leading to enhanced production of arginine within the tumor microenvironment." (PMID 39330508, 2024). "Although ASS1 is required for similar functions in non-transformed and cancerous cells, its loss in cancer cells can provide survival benefits." (PMID 38858597, 2024). "On the other hand, cancer cells can sustain their survival in arginine starvation conditions by inducing ATF4-dependent upregulation of argininosuccinate synthetase 1 (ASS1), allowing de novo arginine synthesis to disrupt T cell function and chromatin remodeling." (PMID 38216787, 2024). "ASS1 is frequently expressed at low levels in numerous cancers." (PMID 38710705, 2024). "Translationally, our data imply that cancer patients and CTLN-I patients with ASS1 loss may be more sensitive to DNA-damaging agents." (PMID 38858597, 2024). "To interrogate whether ASS1 nuclear localization might be cancer-dependent, we fractionated hepatocytes from livers of WT (ASSFlox/Flox) and liver-specific ASS1-KO (Alb-cre) mice." (PMID 38858597, 2024). "However, in many cancer cells, the expression levels of ASS1 are significantly downregulated, leading to an arginine auxotrophic phenotype and a high dependency on extracellular arginine supply." (PMID 37445845, 2023).
cancer (continued). "Similarly, in head and neck cancer, ADI-PEG 20 inhibited cancer cell growth in vitro, and high tumor ASS1 status predicted poor disease-free survival in oral squamous carcinoma patients." (PMID 37445845, 2023). "While this correlation between promoter methylation and reduced ASS1 expression has now been reported more widely across a range of cancers, transcriptional roles have also been suggested for c-Myc and Sp4, as positive regulators, and HIF-1α, as a negative regulator, for arginine biosynthesis." (PMID 36903394, 2023). "More studies are needed to elucidate the complexity of the regulation of ASS1 across cancers." (PMID 36903394, 2023). "In an inverse approach, arginine deprivation by ADI-PEG20 is undergoing clinical trials in ASS1-deficient cancers that depend upon uptake of exogenous arginine, including nonepithelioid MPM." (PMID 36669126, 2023). "Additionally, we also explored the relationship between ASS1 gene alteration and the survival prognosis in different types of cancer." (PMID 38053661, 2023). "Here we explored the gene expression and survival analysis of ASS1 across thirty-three tumors based on the datasets of the TCGA (Cancer Genome Atlas), the GEO (Gene Expression Omnibus), and the GEPIA2 (Gene Expression Profiling Interactive Analysis, version 2)." (PMID 38053661, 2023). "ASS1, one of the urea cycle enzymes, catalyzes the condensation of citrulline and L-aspartate to form argininosuccinate, and this enzyme is downregulated in many types of cancer." (PMID 38283944, 2023). "In MPM cell lines, the LC50 ranged from 9.7 μmol/L to >1.2 mmol/L; however, mizoribine sensitivity appeared unrelated to ASS1 expression or BAP1 status, correlating most closely with proliferative capacity and suggesting MPM are biologically distinct from other ASS1-high cancers." (PMID 36669126, 2023). "ASS1 expression is known to be tightly regulated in cancer cells." (PMID 37254839, 2023). "For example, arginosuccinate synthase (ASS1), which converts nitrogen from ammonia and aspartate to urea, is silenced in several cancers, thus leading to an accumulation of cytosolic aspartate and fostering de novo pyrimidine synthesis to support cancerous proliferation." (PMID 37259925, 2023). "In addition to Hodgkin’s lymphoma and non-Hodgkin’s lymphoma, low expression of ASS1 was observed in additional solid hematological malignancies." (PMID 35814439, 2022). "Based on ASS1 expression, we identified a cluster of advanced ccRCC (ASS1high around 10% of the total cohort of cancers from stage III + IV) in which ASS1 is significantly upregulated compared to stage I + II tumors, consistently with the phenotype observed in 786-M1A cells." (PMID 36539415, 2022). "In these cancers, the promoter of the ASS1 gene is usually epigenetically silenced." (PMID 34599156, 2021). "In a significant number of tumor cells of various cancer types, ASS1 expression is suppressed 12-14, creating cancer's most prevalent metabolic deficiency by rendering cancer cells “addicted” to external arginine and thus vulnerable to arginine-starvation therapy." (PMID 34158865, 2021). "Moreover, another important drawback is that functional analysis of the enzymes expressed in cancer cells and fibroblasts is certainly necessary to strengthen the ASS1/ARG2-based grouping of lung tumors." (PMID 34344457, 2021). "Therefore, the aim of current study was to investigate the antitumor and pro-immunogenic properties of ADI-PEG 20 on ASS1-deficient MC38 and MDA-MB-231 cancer cells in vitro." (PMID 33478072, 2021). "It has been reported that downregulation of urea cycle metabolism, specifically due to decreased expression and activity of ASS1, diverts aspartate towards pyrimidine biosynthesis and supports cell proliferation as part of the metabolic reprogramming in cancer." (PMID 33809510, 2021). "Together, these results suggest that SPA and LM-2I interact with and bind to ASS1 in cancer cells." (PMID 33859183, 2021).
cancer (continued). "Notably, several cancers down-regulate the activity of these pathways via silencing of ASS1 and/or ASNS expression, creating a dependence (auxotrophy) for environmental and/or stromal acquisition of these amino acids." (PMID 33669382, 2021). "The expression of ASS1 in tumors cells can be changed in response to some cancer therapies." (PMID 33859183, 2021). "Indeed, ASS1 was extensively expressed by cancer cells in 75% of tumor analyzed, suggesting that the majority of NSCLCs have an inherent ability to synthesize arginine." (PMID 34344457, 2021). "Arginine deprivation suppresses the growth and induces cell death of ASS1-low cancer cells." (PMID 34298755, 2021). "Therefore, the aim of the current study was to investigate the antitumor and pro-immunogenic properties of ADI-PEG 20 on arginosuccinate synthetase 1 (ASS1)-deficient MC38 and MDA-MB-231 cancer cells in vitro." (PMID 33478072, 2021). "Additionally, the reduction of another enzyme in cancers, argininosuccinate synthase (ASS1), as well as CPS1, elevates cytosolic aspartate levels, thus providing substrates to CAD by facilitating pyrimidine synthesis." (PMID 34638594, 2021). "By rapidly leading to cancer cell death, combination strategies not only achieve effective cytotoxicity but also reduce the likelihood of resistance, such as induced upregulation of ASS1 or production of neutralizing antibody against ADI." (PMID 34299249, 2021). "Therefore, it seems that the discrepancy of the role of ASS1 is related to its expression level in cancers." (PMID 33859183, 2021). "Counterintuitively, however, number of cancers downregulate ASS1 and become arginine auxotrophic." (PMID 34439753, 2021). "This hypothesis of a link between ASS1 and enhanced immune surveillance supports the statistically significant and independent favorable prognostic value of ASS1 expression by cancer cells." (PMID 34344457, 2021). "Indeed, this antagonistic interplay between ARG2-expressing CAFs and TILs resulted in poor prognosis in the current series of patients, despite the arginine synthetic activity of ASS1 expressing cancer cells." (PMID 34344457, 2021). "Auxotrophy, implied by the lack of expression of ASS1 in cancer cells, was associated with high angiogenesis (p < 0.02)." (PMID 34344457, 2021). "Since SPA and LM-2I function as potent ASS1 agonist in cancer cells with low ASS1 expression, it would be very interesting to test whether they also act as ASS1 activator in those nontumor diseases caused by ASS1 deficiency or down-regulation." (PMID 33859183, 2021). "A recent study showed that ASS1P3, a pseudogene of argininosuccinate synthase 1 (ASS1) gene, could function as a ceRNA to regulate its cognate gene and suppress cancer cell proliferation by competing with miR-34a." (PMID 33763422, 2021). "Argininosuccinate synthase (ASS1) was largely expressed by cancer cells." (PMID 34344457, 2021). "ASS1-low cancer cells frequently develop resistance to Arg deprivation monotherapy through genetic alterations and/or metabolic re-wiring, suggesting a need for co-targeting the compensatory mechanisms via rationally designed combination therapy regimens 17-19." (PMID 31903153, 2020). "Interestingly, crosstalk between pyrimidine synthesis and the urea cycle was also detected in a subset of cancer cells with low argininosuccinate synthase (ASS1) expression." (PMID 31108873, 2019). "Yet, the cancer-promoting mechanisms fostered by ASS1 overexpression, and their clinical implications, remain unclear." (PMID 30082427, 2018). "ASS1 expression was downregulated in multiple human cancer types (12 of 14 investigated cancer types; 10 with statistical significance), suggesting that arginine auxotrophy is a common phenomenon in multiple cancer types." (PMID 30393775, 2018). "A variety of cancers display reduced expression of ASS1 and, to a lesser extent, ASL3,4." (PMID 30108309, 2018).